TWIST2 (twist family bHLH transcription factor 2)
Description:
Binds to the E-box consensus sequence 5'-CANNTG-3' as a heterodimer and inhibits transcriptional activation by MYOD1, MYOG, MEF2A and MEF2C. Also represses expression of pro-inflammatory cytokines such as TNFA and IL1B. Involved in postnatal glycogen storage and energy metabolism (By similarity). Inhibits the premature or ectopic differentiation of preosteoblast cells during osteogenesis, possibly by changing the internal signal transduction response of osteoblasts to external growth factors.
Synonyms: bHLHa39; Dermo-1; DERMO1; AMS; BBRSAY; FFDD3; SETLSS
Tractability: PROTAC: ubiquitination databases record sites on it.
Gene: Protein-coding gene on chromosome 2 (238,848,032 to 238,910,534, forward strand). Ensembl gene ENSG00000233608.
Subcellular location: Nucleus; Cytoplasm
Subcellular location (Human Protein Atlas): Nucleoplasm; Nucleoli
Pathways (Reactome):
Cell-Cell communication: Negative Regulation of CDH1 Gene Transcription
Gene expression (Transcription): Transcriptional regulation by RUNX2
Gene Ontology:
Molecular function: protein binding; DNA-binding transcription factor activity, RNA polymerase II-specific; RNA polymerase II transcription regulatory region sequence-specific DNA binding; protein dimerization activity
Biological process: negative regulation of osteoblast differentiation; positive regulation of cell migration; developmental process; negative regulation of DNA-templated transcription; regulation of transcription by RNA polymerase II
Cellular component: cytoplasm; nucleolus; nucleoplasm; nucleus
Genetic constraint (gnomAD): Loss-of-function variants: 1 observed, 6.64 expected, observed/expected ratio (o/e) 0.15, 90% interval 0.052 to 0.71. That is too few expected variants to judge how well the gene tolerates losing a copy. Missense variants: 168 observed, 176.35 expected, observed/expected ratio (o/e) 0.95, 90% interval 0.84 to 1.08. Synonymous variants: 87 observed, 77.99 expected, observed/expected ratio (o/e) 1.12, 90% interval 0.94 to 1.33.
Homologues: Orthologues: dog TWIST2 (100% identical), macaque TWIST2 (100% identical), mouse Twist2 (100% identical), pig TWIST2 (100% identical), rat Twist2 (100% identical), rabbit TWIST2 (99% identical), guinea pig TWIST2 (99% identical), zebrafish twist2 (88% identical), Drosophila melanogaster twi (52% identical), Caenorhabditis elegans hlh-8 (36% identical), Drosophila melanogaster Hand (24% identical), Drosophila melanogaster CG33557 (22% identical), and 3 more. Paralogues in human: TWIST1 (81% identical), PTF1A (34% identical), SCX (31% identical), HAND1 (30% identical), TCF15 (30% identical), HAND2 (29% identical), TCF21 (28% identical), MSC (28% identical), FERD3L (26% identical), FIGLA (26% identical), BHLHA9 (22% identical), TCF24 (22% identical), and 1 more.
Diseases named in the same sentence as TWIST2 in open-access papers:
TWIST2 is named in the same sentence as 104 diseases in open-access papers, as found by Europe PMC text mining. Sharing a sentence is not in itself a finding about the gene and the disease. The quoted sentences say what the papers report.
breast cancer (22 papers, 2012 to 2025). A primary or metastatic malignant neoplasm involving the breast. "In contrast, the fibroblast-like breast cancer cells at the invasion front were characterized by a nuclear localization of Twist2 and loss of E-cadherin." (PMID 23133563, 2012). "In this study we report that Twist2 promotes breast cancer invasion through loss of E-cadherin." (PMID 23133563, 2012). "Clinical pathological characteristics of Twist2-associated breast carcinomas." (PMID 23133563, 2012). "Twist2 may be a potential diagnostic biomarker of breast carcinomas." (PMID 23133563, 2012). "Overexpression of Twist2 can increase the ability of breast cancer cells and mammary epithelial cells to form colonies, promote tumor growth, and increase the number of CD44high/CD24low cell subpopulations and stem cell marker expression." (PMID 30344611, 2018). "The present data indicate that Twist2 staining was a reliable predictor in the prognosis of breast cancer patients." (PMID 23133563, 2012). "In contrast, nuclear Twist2 were detected in cancer cells located at the invasive margins of primary breast cancer." (PMID 23133563, 2012). "We then analyzed the expression and location of Twist2 on the matched breast cancer tissues and normal tissues by immunohistochemical staining." (PMID 23133563, 2012). "The molecular mechanism by which Twist2 participates in EMT of breast cancer in vivo remains poorly understood." (PMID 23133563, 2012). "Collectively, these data indicate that upregulation of cytoplasmic Twist2 is correlated with tumor histological type and tumor metastasis in human breast cancers." (PMID 23133563, 2012). "A comparison of the E-cadherin and Twist2 expression was performed on the adjacent tumor sections of invasive ductal carcinoma (IDC) because this type of tumor accounts for 80% of breast cancers." (PMID 23133563, 2012). "In these fresh breast cancer tissues, Twist2 showed up-regulation in breast carcinomas as demonstrated by western blot analysis." (PMID 23133563, 2012). "To determine Twist2 expression in breast cancers, we initially performed Western blot in human breast carcinoma samples and matched normal breast tissues." (PMID 23133563, 2012). "Of note, endogenous expression of the Zeb1, Zeb2 and Twist2 EMT inducers was also induced, further supporting the association of the EMT interactome with the claudin-low breast cancer subtype." (PMID 22654675, 2012). "Twist2 expression significantly increases and is correlated with tumor histological type and metastasis of breast cancer." (PMID 23133563, 2012). "We showed that Twist2 was up-regulated in human primary breast carcinoma tissues compared with the matched normal breast tissues." (PMID 23133563, 2012). "We examined Twist2 expression pattern in human breast carcinomas by western blot and tissue microarray, and analyzed Twist2 cellular localization by confocal microscopy, cell fractionation and other approaches." (PMID 23133563, 2012). "Twist2 is mainly localized in the cytoplasm of ductal breast carcinomas, and correlated with tumor histological type and tumor metastasis." (PMID 23133563, 2012). "In these breast carcinoma specimens, Twist2 was more often detected in the cytoplasm only (50/105, 48%) or both the cytoplasm and nucleus (38/105, 36%) compared to the nucleus only (17/105, 16%)." (PMID 23133563, 2012). "Additionally, TWIST2 overexpression in breast cancers leads to the downregulation of CDH1 by repressing its promoter." (PMID 40869924, 2025). "Furthermore, using METABRIC data, we found positive correlations between expression of ZFP36 and genes associated with the stem-like phenotype, as TWIST1, TWIST2, SNAI1, ZEB1, ZEB2, ALDH1A and YAP1 in all breast cancer subtypes." (PMID 38274271, 2023).
breast cancer (continued). "Previous experience in breast cancer showed that Twist2 overexpression not only promoted EMT signaling, but also enhanced colony-forming abilities of stem cells, which suggested that Twist2 may be a master inducer of both EMT and CSC features." (PMID 28245823, 2017). "Twist2 has been shown to promote tumor progression through EMT in breast cancer." (PMID 24244294, 2013). "Twist2 has been shown to promote human tumor invasion as in breast cancer and cervical cancer." (PMID 24244294, 2013). "But how Twist2 participates in EMT of breast cancer in vivo remains poorly understood." (PMID 23133563, 2012). "Assessment of Twist2 expression status may provide clinically useful prognostic information in patients with breast cancer." (PMID 23133563, 2012). "Twist2 expression was significantly increased in breast cancer." (PMID 23133563, 2012). "Taken together, our results suggest that nuclear Twist2 may activate EMT transiently in the tumor invasion front, while cytoplasmic Twist2 contributes to the maintenance of epithelial cancer characteristics in tumor center or LM metastases in breast cancer." (PMID 23133563, 2012). "It has been reported that Twist2 could activate EMT programs to facilitate a cancer stem cell phenotype in breast cancer recently." (PMID 23133563, 2012). "Our data demonstrate that Twist2 is up-regulated in breast carcinomas." (PMID 23133563, 2012). "The expression of Twist2 in cytoplasm and nucleus of breast carcinomas." (PMID 23133563, 2012). "In contrast, Twist2 was detected in breast carcinoma tissues." (PMID 23133563, 2012). "To determine the expression pattern of Twist2 in breast carcinomas, we performed immunohistochemical staining of Twist2 on a tissue microarray that includes 7 cases of normal breast tissue, 6 cases of fibroadenoma, 13 cases of mammaryadenosis, 16 cases of mastitis, and 141 cases of breast cancer." (PMID 23133563, 2012). "TWIST1 and TWIST2 have previously been described as playing a distinct role during embryonic development and having anti-correlated transcriptional expression patterns in spontaneous focal mammary tumors in mice and in human melanoma, colon, kidney, lung, and breast cancer." (PMID 35022561, 2022). "Consequently, it has been shown that suppression of AKR1B1 inhibits the expression of RelA and Twist2 while its overexpression could induce RelA and Twist2 in various cell lines of breast cancer." (PMID 32633024, 2020). "Twist2 might be a new candidate for tumor metastasis of breast cancer." (PMID 23133563, 2012). "In addition, we detected a heterogeneous expression pattern of Twist2 within breast cancers." (PMID 23133563, 2012). "However, little is known on the functional significance of Twist2 expression in breast cancer." (PMID 23133563, 2012). "Quantitative gene expression analysis was performed to assess the transcription of EMT (epithelial–mesenchymal transition) markers Slug, Snail, Twist2, and Zeb1 in trastuzumab-resistant HER2-positive breast cancer cells." (PMID 39201327, 2024). "In line with this, the TCGA breast cancer (Metabric) dataset shows a strong inverse correlation of RNA expression between PML and TWIST2." (PMID 37518985, 2023). "Significant downregulation of the miR-200 family, which consists of miR-141, miR-200a, miR-200b, miR-200c, and miR-429, regulates the expressions of mesenchymal markers ZEB1, ZEB2, TWIST1, TWIST2, Snai1, and Snai2 and promotes EMT in breast cancer." (PMID 37533517, 2022). "It has been also indicated that Twist2 is highly expressed in breast cancer and nuclear Twist2 plays a role in inducing EMT in breast cancer." (PMID 32633024, 2020). "In basal-like breast cancer, an aggressive triple-negative subtype of mammary cancer, AKR1B1 is transcriptionally activated by Twist2 and sustains a positive feedback loop involving NF-κB activation via PGF2A, thereby reinforcing EMT and enhancing tumor invasiveness." (PMID 41154825, 2025).
breast cancer (continued). "Moreover, positive correlation and direct interaction of Twist2 and AKR1B1 have been indicated in breast cancer." (PMID 32633024, 2020). "Twist2 activates EMT programs and promotes a cancer stem cell phenotype in breast cancer." (PMID 24244294, 2013). "No positive expression of Twist2 was detected in 7 normal breast samples or adjacent normal breast tissues in 32 breast cancer patients." (PMID 23133563, 2012). "Twist2 activates EMT programs and facilitates a cancer stem cell phenotype in breast cancer." (PMID 23133563, 2012). "Cells with cytoplasm Twist2 showed no obvious change in cellular morphology with strong membranous or cytoplasm expression of E-cadherin in primary breast cancers or metastases." (PMID 23133563, 2012). "However, the role of Twist2 in promoting breast cancer invasion and metastasis has not been established in the context of the breast microenvironment." (PMID 23133563, 2012). "In addition, the identification and clinical relevance of Twist2 in breast cancer is not known." (PMID 23133563, 2012). "Consequently, induced expression of AKR1B1 by Twist2 could regulate E‐cadherin which its suppression has been seen to induce migration and invasion regardless of EMT in breast cancer." (PMID 32633024, 2020).
cervical carcinoma (11 papers, 2012 to 2022). A carcinoma arising from either the exocervical squamous epithelium or the endocervical glandular epithelium. "It has been reported that over-expression of Twist2 was significantly linked to cervical carcinoma metastasis." (PMID 24751719, 2014). "Only recently, convincing evidence showed that Twist2 overexpression was significantly linked to cervical cancer progression." (PMID 24244294, 2013). "For hsa-miRNA-221-3p, cell cycle regulation has been reported as a key mechanism in tumor progression; in addition, in cervical cancer, increased expression levels are associated with epithelial-mesenchymal transition, migration, and invasion by targeting TWIST2." (PMID 31467538, 2019). "Twist2 overexpression was significantly linked to cervical cancer progression recently." (PMID 23133563, 2012). "For instance, miR-221-3p is transcriptionally activated by Twist family BHLH transcription factor 2 (TWIST2) and enhances cell migration, invasion, and lymphatic metastasis in cervical cancer." (PMID 33799952, 2021). "As TWIST2 has been shown to be negatively correlated with THBS2 in cervical cancer, we transfected LINC01235 overexpression plasmids into HGC-27 and SGC-7901 cells." (PMID 33206629, 2020). "Here, we showed that the transfection of Gankyrin markedly up-regulates Vimentin, Twist2, β-catenin and down-regulates E-cadherin in cervical carcinoma cells." (PMID 24751719, 2014). "In vitro, the transfection of Gankyrin resulted in markedly up-regulating of Vimentin, β-catenin and Twist2, as well as down-regulating of E-cadherin in cervical carcinoma cells." (PMID 24751719, 2014). "Twist2 is a potential prognostic marker for cervical cancer, adenoid cystic carcinoma, and tongue squamous cell carcinoma." (PMID 24244294, 2013). "As the hallmarks of EMT, the up-regulation of Vimentin, Twist2, β-catenin and the down-regualation of E-cadherin caused by the transfection of Gankyrin forcefully indicated Gankyrin’s facilitation effect towards EMT of cervical carcinoma." (PMID 24751719, 2014). "In cervical cancers, in comparison to TWIST1, TWIST2 may better stratify patients into prognostic subgroups and is shown to induce EMT and cell motility in cell lines." (PMID 25528769, 2015). "Twist2 has been shown to be an important inducer of EMT in breast and cervical cancer." (PMID 24244294, 2013).
ablepharon macrostomia syndrome (10 papers, 2017 to 2022). "Mutations of TWIST2 have been associated with ectodermal dysplasia, such as Ablepharon-Macrostomia syndrome and Barber-Say syndrome whose manifestations include dysmorphic ears." (PMID 36035146, 2022). "Clinical studies report specific mutation of TWIST2 is observed in patients with Ablepharon macrostomia syndrome (AMS) and Barber–Say syndrome (BSS)." (PMID 31964350, 2020). "Ablepharon macrostomia syndrome (AMS) is a rare congenital malformation disorder caused by the autosomal-dominant mutations in gene TWIST2." (PMID 31462237, 2019). "Moreover, zAncBE4max successfully generated the Twist2 p.E78K mutation in zebrafish, recapitulating pathological features of human ablepharon macrostomia syndrome (AMS)." (PMID 33272268, 2020).
hepatocellular carcinoma (8 papers, 2017 to 2025). A malignant tumor that arises from hepatocytes. "For instance, in a hepatocellular carcinoma model, ACOT12 deficiency-induced acetyl-CoA accumulation specifically increased histone acetylation at the Twist2 locus." (PMID 40589742, 2025). "In conclusion, our study demonstrated that circ_0067835 contributed to promoting hepatocellular carcinoma cell proliferation and metastasis through downregulating miR-1236-3p expression and then elevating Twist2 expression, which might provide a new vision for HCC patients." (PMID 36262967, 2022).
kidney cancer (8 papers, 2017 to 2025). Primary or metastatic malignant neoplasm involving the kidney. "Twist2 promotes cell proliferation and is involved in the progression of kidney cancer by the ECM-receptor interaction pathway." (PMID 38370370, 2024). "It has been reported that Twist2 promoted kidney cancer cell proliferation and invasion by upregulating ITGA6 expression in the ECM-receptor interaction pathway." (PMID 31832114, 2019). "As a member of the basic helix-loop-helix (bHLH) family which plays a key role in tumorigenesis, Twist2 could promote proliferation and invasion of kidney cancer cell via regulating the ECM-Receptor-Interaction pathway." (PMID 28410203, 2017). "Twist2 is known to regulate ITGA6 and CD44 expression in the ECM-receptor interaction pathway to promote kidney cancer cell proliferation and invasion." (PMID 41450820, 2025). "A study reported that Twist2 regulates the expressions of CD44 and ITGA6 in the ECM-receptor interaction pathways, thereby stimulating the invasion and proliferation of kidney cancer cells." (PMID 35028418, 2022). "It was previously reported that Twist2 transcriptionally regulates the ECM-receptor interaction pathway and contributes to kidney cancer cell proliferation and invasion." (PMID 33531976, 2021).